RASSF2 (Ras association domain family member 2)
Diseases named in the same sentence as RASSF2 in open-access papers (continued):
Sharing a sentence is not in itself a finding about the gene and the disease.
tumor (33 papers, 2005 to 2025). "The protein encoded by the RASSF2 gene has been found to be a potential tumor suppressor and can act as a KRAS-specific effector protein." (PMID 34745226, 2021). "Consistent with this possible mechanism, the Ras association domain family member 2 (RASSF2) tumor suppressor has been shown to bind a cl-Par-4-sized fragment of Par-4, via the NLS." (PMID 30518159, 2018). "RASSF2 is a tumor suppressor that shares homology with other Ras-association domain (RASSF) family members." (PMID 26999212, 2016). "As concerns RASSF2, its downregulation was detected only at tumor stage and was closely associated with elevated serum alpha-fetoprotein level, but not significantly with clinical stage and hepatic fibrosis." (PMID 22548173, 2012). "Next, we analyzed the distinct tumor suppressive features associated with RASSF2." (PMID 20920251, 2010). "In addition, Ras association domain families 1 and 2 (RASSF1 and RASSF2), the negative regulators of K-ras, are often inactivated by methylation of the promoter region in those tumours." (PMID 17923875, 2007). "Thus, inactivation of RASSF2 confers a growth advantage to tumor cells harboring activated K-Ras, and loss of RASSF2 expression may be a key event in Ras-mediated transformation." (PMID 22693671, 2012). "RASSF2 and RASSF5 belong to the RASSF family that shares a region of homology (the Ras association domain), and RASSF proteins functions as tumor suppressors by interacting either directly or indirectly with activated Ras and regulating cell growth signaling." (PMID 34604090, 2021). "It was revealed that RASSF2 inhibits tumor cell growth, suggesting that it is a tumor-suppressor gene in CRC." (PMID 33968341, 2021). "To further confirm the requirement of Hippo kinases for RASSF2-mediated tumor suppression we generated mice with conditional gene inactivation of both MST1 (Stk4) and MST2 (Stk3) in hematopoietic cells (Vav1-Cre)." (PMID 32029705, 2020). "These evidences revealed that RASSF2 was a novel K-Ras-specific effector and potential tumor suppressor." (PMID 27901488, 2017). "RASSF2 has previously been reported to interact with the MST kinases in the cytoplasm and cytoplasmic RASSF2 retains its tumor suppressor activity." (PMID 26999212, 2016). "In summary, to gain a better insight into the mechanism of action of the RASSF2 tumor suppressor, we have identified novel interactions between RASSF2 and proteins regulating diverse biological activities." (PMID 26999212, 2016). "RASSF2 also interacts with the PAR-4 tumor suppressor and modulates its nuclear translocation, an essential process required for PAR-4 activity." (PMID 26999212, 2016). "RASSF2 behaves as a tumor suppressor in that its overexpression promotes apoptosis and cell cycle arrest in vitro and inhibits tumor growth in vivo, and loss of RASSF2 expression results in enhanced invasion, growth in soft agar, and transformation." (PMID 26999212, 2016). "Different patterns of RASSF2 expression for distinct tumor subtypes were detected by immunohistochemistry." (PMID 26284587, 2015). "According to RASSF2 hypermethylation, the hazard ratio for survival was 2.16 (95% CI = 0.91, 5.1) after adjusting for age and tumor grade." (PMID 25621889, 2015). "In this study, RASSF1 and RASSF2 were hypermethylated in cell lines representative of tumor subtypes with best and worst prognosis, respectively." (PMID 26284587, 2015). "RASSF2 hypermethylation differed between tumor subtypes as defined by the St Gallen 2013 criteria (i.e., luminal A-like, luminal B-like/HER2-negative, luminal B-like/HER2-positive, HER2-positive, and triple-negative) (p = 0.005)." (PMID 26284587, 2015). "RASSF2 is a novel tumor-suppressor gene that has been shown to play an important role in the Ras signaling pathway." (PMID 25298284, 2014). "The mouse model suggests a role of RASSF2 in bone development, but also tumor suppressive properties were reported." (PMID 24252868, 2013).
tumor (continued). "The RASSF2 transcript was detected in normal tissue, but was shown to be down regulated by hypermethylation of its promoter region in various tumor entities." (PMID 24252868, 2013). "For the RASSF2 promoter a total of 43 tumor samples were analyzed and 7% of these showed hypermethylation." (PMID 24252868, 2013). "With a total of 43 analyzed tumor samples RASSF2 seems to be hypermethylated in only a small subset of samples." (PMID 24252868, 2013). "RASSF2 has the properties of a tumor suppressor in that its overexpression promotes apoptosis and cell cycle arrest in vitro and inhibits tumor cell growth and tumor xenograft formation in nude mice." (PMID 22693671, 2012). "Inactivation of RASSF2 enhances K-Ras-mediated transformation and overexpression of RASSF2 suppresses tumor cell growth." (PMID 22693671, 2012). "RASSF2 exhibits several tumor suppressor properties, like inhibition of cell growth and induction of apoptosis." (PMID 20920251, 2010). "In summary, our data suggest that RASSF2 tumor suppression function involves apoptotic regulation through binding of the proapoptotic kinases MST." (PMID 20920251, 2010). "RASSF2 inhibits the growth of tumour cells, promotes both cell cycle arrest and apoptosis, and is frequently downregulated in lung tumour cell lines." (PMID 16265349, 2005). "On the other hand, circ_0001666, a down-expressed exonic circRNA, could be a tumor suppressive circRNA in CRC through sponging miR-1276 in the circ_0001666/miR-1276/RASSF2 axis." (PMID 33968341, 2021). "The hypermethylation status of the RASSF2 promoter could be a poor prognostic factor, as its hypermethylation would promote tumour cell aggressiveness." (PMID 34885067, 2021). "Patients were classified according to whether their tumour strongly (n = 336) or weakly (n = 102) expresses the RASSF2 mRNA." (PMID 34885067, 2021). "Three of the RAS-association domain family members (RASSF2, RASSF3, and RASSF5) were involved in the network analysis using all methylomics decision tree models, which are known as tumor suppressor genes and epigenetically inactivated in different tumor types." (PMID 31552087, 2019). "A previous study demonstrated that PAR-4 was a direct binding partner of RASSF2 and the lower expression of RASSF2 could impaire the PAR-4-driven apoptosis in tumor cells." (PMID 27901488, 2017). "RASSF2 hypermethylation was confirmed by bisulfite sequencing (BS) in clones derived from normal tissue adjacent to the tumor, completely normal tissue and from tumor samples." (PMID 26284587, 2015). "Similar to RASSF2, only a small number of tumor samples harbor a RASSF5C promoter hypermethylation." (PMID 24252868, 2013). "Corresponding results were, for CDH1 (1 tumor with mean >10% and 1 additional tumor with max at 17%), for RASSF2 (1 tumor + 24 tumors up to 15%), for DCR2 (5 tumors + 3 tumors up to 39%), for RASSF1A (23 tumors + 1 up to 31%), and for CASP8 A1 (21 tumors + 2 tumors up to 21%)." (PMID 22984959, 2012). "As previously reported, methylation of RASSF2 in those tumours may be affected by CpG island methylator phenotype status." (PMID 17923875, 2007). "Therefore, there may be a clinical interest in studying the hypermethylation status of the RASSF2 promoter in CRC tumours as a prognostic factor in order to adapt the therapeutic management." (PMID 34885067, 2021). "Therefore, we hypothesized that RASSF2-mediated tumor suppression against RUNX1-ETO-expressing cells may be dependent on SARAH domain-dependent stabilization by the Hippo kinases." (PMID 32029705, 2020). "One interesting candidate was RASSF2, a Ras effector, which found to be downregulated in both proteome datasets, it connects RAS to various signaling pathways, potentially influencing tumor growth and progression." (PMID 39833546, 2025).
tumor (continued). "Collectively, it can be proposed that under-expression of both circ_0001666 and circ_0000977, as tumor suppressive circRNAs, contributes to the down-regulation of some tumor suppressive genes in CRC, including RASSF2, IL10RA, and AKR1B10." (PMID 33968341, 2021). "The inactivation of RASSF2 enhances K-RAS-mediated transformation, and overexpression of RASSF2 suppresses tumor cell growth, as described in another study." (PMID 26284587, 2015). "The focus of our current work was on RASSF2, RASSF5A, RASSF5C and RASSF10, due to the fact that epigenetic inactivation of these tumor suppressors of the RASSF family was already reported in different cancer types." (PMID 24252868, 2013). "In summary we were able to show different RASSFs like RASSF2, RASSF5C and RASSF10 are tumor specifically methylated at their promoter region in MCC, additional to the earlier reported presence of RASSF1A hypermethylation in MCC." (PMID 24252868, 2013). "In the tumor panel, increased promoter methylation was observed in BLU, CASP8, DCR2, CDH1, RASSF1A and RASSF2, possibly providing the second hit for BLU, RARB and RASSF1A." (PMID 22984959, 2012). "Thus, RASSF2 may act as a scaffold integrating multiple tumor suppressor pathways." (PMID 22693671, 2012). "RASSF2, a member of the RASSF1 family, has recently been identified as a potential tumour suppressor." (PMID 16265349, 2005). "While it is well established that RASSF2 is a bona fide K-Ras effector and powerful tumor suppressor, its modes of action are not well defined." (PMID 26999212, 2016). "RASSF2 has no apparent intrinsic enzymatic activity or DNA binding properties and thus acts by interacting with other proapoptotic effectors and tumor suppressors, including PAR-4 and the MST1/2 kinases, thereby regulating the pathways these effectors control." (PMID 22693671, 2012). "Since RASSF5A methylation was not tumor specific, we further focused on RASSF2 where methylation was preferentially found in cancers." (PMID 20920251, 2010). "RASSF2 was identified as a third member of the RASSF1 family and a ras effector/tumour suppressor." (PMID 16265349, 2005). "The exact mechanism by which RASSF2 functions is not clearly defined, but it likely acts as a scaffolding protein, modulating the activity of other pro-apoptotic effectors, thereby regulating and integrating tumor suppressor pathways." (PMID 26999212, 2016).
cancer (28 papers, 2007 to 2025). A tumor composed of atypical neoplastic, often pleomorphic cells that invade other tissues. "To well demonstrate the role of RASSF2-PAR-4 signaling axis in miRNA-7-associated CAF-driven cancer cell growth, we have designed a series of in vitro experiments." (PMID 27901488, 2017). "RASSF2 is a pro-apoptotic effector in a variety of tumors, and a loss of RASSF2 expression enhanced the proliferation and migration of cancer cells." (PMID 27901488, 2017). "It is described that the RASSF2 promoter is frequently hypermethylated in many types of cancers, such as bronchopulmonary, gastric, colorectal, breast, endometrial, and upper aerodigestive cancers." (PMID 34885067, 2021). "Methylation of RASSF1, RASSF2, RASSF3, RASSF6, RASSF7, and RASSF9, from the RASSF regulator family was strongly associated with expression of several GMDs in a variety of cancer categories." (PMID 33676569, 2021). "The RASSF2 gene promoter is frequently hypermethylated in many types of cancers, such as bronchopulmonary, gastric, colorectal, breast, endometrial, and upper aerodigestive cancers." (PMID 34885067, 2021). "RASSF2 is a tumor suppressor gene and was proposed as a novel methylation marker for screening several cancers." (PMID 31552087, 2019). "Many published studies have demonstrated that the RASSF2 gene is silenced by promoter methylation in numerous human cancers." (PMID 27901488, 2017). "In our study we showed that the RASSF2 promoter region was hypermethylated in 7% of cancer samples, but unmethylated in control tissue." (PMID 24252868, 2013). "After selection for 4 weeks a 65% decrease of colony formation in cancer cells transfected with RASSF2 (mean = 4.6) compared to cells transfected with the empty vector (mean = 13.6; p = 0.019, one-way ANOVA test) was observed." (PMID 20920251, 2010). "In addition, several of the promoter-hypermethylated genes were associated with the development of human cancers and these include GIPC2, DIRAS3, TYSPL6, EDNRB, FYN, GDNF, RASSF1, and RASSF2." (PMID 21962230, 2011). "The role of the RASSF2 gene in cancer remains largely unknown." (PMID 25621889, 2015). "Interestingly, RASSF5A and RASSF2 methylation was reduced in MTC compared to other cancers." (PMID 20920251, 2010). "RASSF2, similar to RASSF1A, is transcriptionally silenced in several cancer types and knockdown has previously been demonstrated to promote cell proliferation and more aggressive phenotypes in lung cancer." (PMID 32029705, 2020). "Overexpression of miR-7 in CAFs led to down-regulation of RASSF2, which dramatically decreased the secretion of PAR-4 from CAFs and then enhanced the proliferation and migration of the co-cultured cancer cells." (PMID 27901488, 2017). "Up-regulated miR-7 negatively controlled the target gene RASSF2 expression, which then decreased the secretion of PAR-4 into the cancer microenvironment." (PMID 27901488, 2017). "The overexpression of miR-7 negatively controlled the expression of target gene RASSF2, which then decreased the secretion of the PAR-4 protein into the cancer microenvironment." (PMID 27901488, 2017). "EPB41L3, RASSF2 and TSP-1 genes were hypermethylated only in tumors (29%, 10.6%, and 50%, respectively), confirming their cancer-specific role." (PMID 25621889, 2015). "Finally, RASSF2 was amongst the most decreased proteins, implying the importance of BRAT1 potentially influencing cancer cell invasion." (PMID 39833546, 2025). "Hence, the strong TS genes SASH1, STARD13, RECK, CBFA2T3, RASSF2, RAP1A, and ARHGEF12 can be used as specific biomarkers for diagnosis of NSCLC cancer." (PMID 33580150, 2021). "In head and neck cancers, overexpression of miR-7 in CAFs leads to downregulation of RASSF2, which greatly reduces the secretion of protease-activated receptor 4 (PAR-4), a proapoptotic factor in cancer cells, thus leading to enhancement of cancer cell proliferation." (PMID 33213510, 2020).
cancer (continued). "Similarly, our study revealed that RASSF2 directly controlled the expression of PAR-4, thereafter inducing apoptosis in cancer cells." (PMID 27901488, 2017). "Similarly, levels of DNA methylation in RASSF2, SOX5, GALNT14 and miR-34b/c, four cancer-related genes, were strikingly higher in lesions located in the proximal colon (from the cecum to the descending colon) than in those in more distal subsites." (PMID 27145369, 2016). "In addition, we also found that the presence of HDAC7 led to the upregulation of genes related to immune processes (IL16, FCGR2A, IRAK2, CD86 and CD40, among others) and cancer (RASSF4, RAB31, NEDD9 and RASSF2, among others)." (PMID 25675295, 2015). "We found RASSF2 to be methylated in three out of 43 (7%), RASSF5A in 17 out of 39 (44%, but also 43% in normal tissue), RASSF5C in two out of 26 (8%) and RASSF10 in 19 out of 84 (23%) of the cancer samples." (PMID 24252868, 2013). "No studies have addressed the presence or the prognostic role of EPB41L3 and RASSF2 hypermethylation in diffuse gliomas, and there have been few studies of TSP-1; the hypermethylation of these genes is known to be clinically significant in other types of cancers." (PMID 25621889, 2015).
infection (1 paper, 2025). The state of being infected such as from the introduction of a foreign agent such as serum, vaccine, antigenic substance or organism. "For example, we observe significant HCMV-induced loss of TEAD1 binding, chromatin accessibility, and H3K27ac levels proximal to the promoters of the Hippo pathway genes FRMD6 and RASSF2, both of which have significantly diminished gene expression subsequent to infection (see next section)." (PMID 40928347, 2025).
RASSF2 also shares sentences with these, for which no sentence is quoted: endometriosis (2 papers); osteoporosis (2); acute lymphoblastic leukemia (1); autoimmune disease (1); brain inflammation (1); cervical cancer (1); colon adenoma (1); follicular adenomas (1); gastric adenocarcinoma (1); goiter (1); hematologic cancer (1); intraepithelial neoplasia (1); neurofibromatosis type 1 (1); non-small cell lung carcinoma (1); Obesity (1); plexiform neurofibroma (1); prostate tumor (1); rectal carcinoid tumors (1); squamous cervical cancer (1); viral infections (1).